IL6 (interleukin 6)
Diseases named in the same sentence as IL6 in open-access papers (continued):
Sharing a sentence is not in itself a finding about the gene and the disease.
autoimmune disease (continued). "Dysregulation of IL-6 can also cause chronic inflammation and autoimmune diseases." (PMID 39771147, 2024). "Notwithstanding this, the investigation of the main HFE mutations and the −174G>C polymorphism in the IL-6 promoter may add some information on the interplay linking iron metabolism, inflammation and immunity in autoimmune diseases such as SLE and RA." (PMID 38003490, 2023). "The IL6 gene encodes the protein interleukin-6 (IL-6), a cytokine with multiple functions associated with immune responses and inflammation; therefore, it has been closely related to the pathology of different chronic inflammatory and autoimmune diseases." (PMID 37887075, 2023). "IL-6 overproduction has been linked to a number of autoimmune disorders, including MS." (PMID 37535585, 2023). "IL6 (interleukin 6) encodes a cytokine that functions in many autoimmune diseases or infections." (PMID 36338963, 2022). "The TGF-β and IL-6 induce differentiation of pathogenic IL-17, producing T-helper 17 (Th17) subsets that may promote inflammation and enhance autoimmune disease." (PMID 36397759, 2022). "In addition to these antibodies known to be associated with autoimmune diseases, other antibodies such as autoantibodies against type I-IFNs or directed against other cytokines including GM-CSF, IL-6, and IL-10 have also been identified." (PMID 35453524, 2022). "However, prolonged synthesis of IL-6 has a pathological effect on chronic inflammation and can predispose patients to the development of malignancies and autoimmune diseases." (PMID 35707129, 2022). "Importantly, the pro-inflammatory pleiotropic cytokine IL-6 is associated with neoplasia and autoimmune diseases." (PMID 35955708, 2022). "Similarly, THP-1 cells trained with serum from patients with childhood-onset SLE (cSLE) – another type I IFN-associated autoimmune disease – produced slightly higher levels of IL-6 after Pam3Cys re-stimulation." (PMID 35860283, 2022). "Blocking TNF-α causes a decline in IL-1 and IL-6, as well as adhesion molecules and vascular endothelial growth factors (VEGFs), and in disorders such as autoimmune diseases, TNF blockers are being suggested to be used in hospitalized patients with severe inflammatory response." (PMID 33946736, 2021). "In addition, cytokines, such as IL6, are highly implicated in the development and progression of multiple autoimmune diseases whose production can be regulated by EV packaging and secretion." (PMID 32547552, 2020). "Recent studies have shown that curcumin ameliorates autoimmune diseases by regulating inflammatory cytokines such as IL-1beta, IL-6, IL-12, TNF-alpha and IFN-gamma and associated JAK-STAT, AP-1, and NF-κB signaling pathways in immune cells, as reviewed by others." (PMID 32143311, 2020). "IL6 has been implicated in the pathogenesis of autoimmune disease." (PMID 32689994, 2020). "Another study with mice autoimmune encephalomyelitis models showed that Th17, IL-6, and IL-17 concentration increases may be associated with autoimmune disorders of central nervous system (CNS)." (PMID 29736281, 2018). "A variety of autoimmune diseases are associated with high levels of IL-6 production." (PMID 28134847, 2017). "In summary, the IL-6 - Th-17 - IL-17 pathway may play a pathogenic role in mediating the irAEs and/or autoimmune exacerbations of patients with an underlying autoimmune disease treated with immunotherapy and deserves further study." (PMID 27595932, 2016). "However, heightened expression of IL6 has also been associated with a range of pathologies including a variety of autoimmune diseases in humans and mice." (PMID 27050763, 2016). "A variety of autoimmune diseases are associated with an excessive IL-6 production." (PMID 26193267, 2015). "In addition, benfotiamine reduced expression and release of TNF-α and IL-6, which are the cytotoxic mediators linked with the development of chronic inflammatory and autoimmune diseases." (PMID 25695433, 2015).
autoimmune disease (continued). "However, cytokines such as IL-6 are critical mediators of the autoimmune diseases and IL-6 is implicated in several disease processes." (PMID 25674084, 2014). "Signaling abnormalities in IL-6 could lead to an autoimmune disease or increased susceptibility to infection." (PMID 23424706, 2012). "Acute IL-6 synthesis provides a warning signal and protects the host from environmental stress, while its prolonged production causes the onset and progression of various autoimmune diseases." (PMID 22315615, 2012). "IL-6–deficient mice are resistant to various experimentally induced autoimmune diseases." (PMID 21031020, 2010). "However, aged MRL/lpr mice, genetically predisposed to the development of autoimmune diseases and reported to have elevated levels of IL-6 and sIL-6R levels, had a marked downregulation of gp130 in splenic T cells." (PMID 20671912, 2010). "Several cytokines, including IL-6, have been implicated in the pathogenesis of autoimmune diseases." (PMID 21209948, 2010). "A causative role for IL-6 in autoimmune disease was first recognized by the observation that the autoimmune symptoms of patients with cardiac myxomas, such as hyper-γ-globulinemia and autoantibody production, disappeared with resection of the tumor that produced IL-6." (PMID 19228423, 2009). "Additionally, IL-6 is implicated in the pathogenesis of multiple autoimmune diseases such as rheumatoid arthritis, vasculitis and various auto-inflammatory disorders that all could accelerate atherogenesis as well as certain types of cancer." (PMID 41543641, 2026). "Improvement of sleep quality after IL-6 or TNF receptor antagonists treatments in patients with autoimmune diseases didn’t appear to directly result from decreased disease activity, suggesting that abnormal regulation of IL-6 and TNF may be associated with sleep disturbances." (PMID 37161304, 2023). "Additionally, IL-6 plays a critical role in chronic inflammation, autoimmune diseases, infectious diseases, metabolic diseases, and cancer, and thus the IL-6 cytokine family has been used as a diagnostic or prognostic indicator of disease activity and response to therapy." (PMID 35719915, 2022). "Therefore, it is speculated that rs2228145 impairs classical IL-6/IL-6R signaling and reduces the inflammatory response, thus leading to a lower risk of CVDs, inflammatory, or autoimmune diseases." (PMID 35493452, 2022). "However, IL-6 trans-signaling pathway (mediated by an interaction between IL-6/soluble IL-6R complex with gp130 subunit) has been implicated in the pathogenesis of malignant, inflammatory and autoimmune diseases." (PMID 33671821, 2021). "In addition, the inhibitory effect of DDZ on IL-6-induced STAT3 activation may be associated with its potential beneficial application against autoimmune diseases." (PMID 31878046, 2019). "The RANKL-dependent regulation of osteoclast formation by IL-6/sIL-6R might reflect pathological processes of the local microenvironment in autoimmune diseases associated with bone destruction, such as RA, and whether this effect is stimulatory or inhibitory may be dependent on disease stage." (PMID 28128332, 2017). "Pro-inflammatory cytokines such as IL-1β and IL-6 are generally associated with the stimulation of inflammation and autoimmunity, and may also stimulate production of T regulatory lymphocytes, inhibiting the development of autoimmune diseases." (PMID 29133889, 2017). "However, since the overproduction of IL-6 and abnormalities in IL-6 signal transduction might be causative factors in several autoimmune disorders, the IL-6 blockade might be an effective approach in their treatment." (PMID 24489578, 2013). "When IL-6 levels are elevated, as seen in chronic inflammation or autoimmune diseases, there is increased activation of these promoter elements, leading to higher synthesis of apolipoprotein(a) and consequently increased Lp(a) concentrations in the blood." (PMID 41543641, 2026).
autoimmune disease (continued). "More selective approaches include biological agents such as IL-6 inhibitors, which are approved for autoimmune diseases." (PMID 41608286, 2026). "The impact of immunotherapeutic agents targeting specific genes, such as anti-IL-7R 13, anti-IL-6 15 and immune checkpoint inhibitors 16, their effect on cancer and autoimmune diseases is receiving extensive scrutiny." (PMID 39744497, 2025). "None of the reviewed evidence suggests we are ready to treat migraines with cytokine inhibitors directly (as is done in some autoimmune diseases), but it opens the door to research on, say, IL-6 inhibitors or TNF inhibitors in refractory CM." (PMID 41377228, 2025). "Inflammatory cytokines such as tumor necrosis factor-alpha (TNF-α), interleukin-1 beta (IL-1β), and interleukin-6 (IL-6) are elevated in many autoimmune diseases and contribute to the inflammatory milieu." (PMID 39856066, 2025). "Although autoimmune diseases exhibit a wide range of pathophysiological mechanisms, common inflammatory markers such as IL-6, TNF-α, and interferon-gamma (IFN-γ) play a role in both autoimmunity and neuroinflammatory processes." (PMID 40002916, 2025). "IL-6 is known to play a key role in various autoimmune diseases, with significantly elevated levels in the synovial fluid of RA patients." (PMID 40655145, 2025). "IL-6 is a key pro-inflammatory cytokine involved in chronic inflammation and autoimmune diseases, including TED." (PMID 40807149, 2025). "Nevertheless, the effect of lactylation on T-cell differentiation via TGF-β signaling in IL-6-related autoimmune diseases remains to be further investigated." (PMID 40655145, 2025). "Mice deficient in various aspects of the JAK/STAT signal transduction pathway utilized by IL-6/IL-12 cytokines have also provided mechanistic insights on how proinflammatory T cell subsets contribute to the development of autoimmune diseases." (PMID 40114923, 2025). "IL-6, abundantly present in the synovial fluid of RA patients, plays a pivotal role in various chronic inflammatory and autoimmune diseases." (PMID 40406113, 2025). "IL-6 is an important immunomodulator, and IL-6 can be discovered in serum of patients with autoimmune diseases and inflammatory reactions." (PMID 40469159, 2025). "It is well documented that in autoimmune diseases, ABCs can exhibit unique cytokine profiles distinct from other B cells, including the production of pro-inflammatory mediators like IL-6, IFN-γ, and TNF-α." (PMID 40917658, 2025). "Numerous studies have highlighted the critical role of IL6 signaling in the pathogenesis of autoimmune diseases, including Graves’ orbitopathy (GO)." (PMID 40018034, 2025). "The results of this study underscore the crucial function of interleukin-6 (IL-6) as an element with diversified function in the modulation of the immune response, especially in the pathogenesis of autoimmune diseases and inflammation." (PMID 39996755, 2025). "As a pleiotropic pro-inflammatory cytokine, IL-6 is involved in chronic inflammation as well as autoimmune diseases and is often used to indicate the occurrence of inflammation." (PMID 40625742, 2025). "While tocilizumab's primary mechanism involves inhibiting IL-6 signaling, leading to reduced inflammation in autoimmune diseases, its potential role in modulating allergic responses warrants further investigation." (PMID 40130131, 2025). "IL-6 is a key driver of Th17 differentiation, critical in the pathogenesis of autoimmune diseases like systemic JIA." (PMID 40130131, 2025). "IL-6 serves as a key immunomodulatory cytokine, influencing the pathogenesis of autoimmune diseases, chronic inflammatory conditions, cancers, and other disorders." (PMID 40170729, 2025). "Existing treatments targeting cytokine pathways, such as IL-6 inhibitors, are already in use for other autoimmune diseases, suggesting potential applicability in RHD management." (PMID 39618620, 2024).
autoimmune disease (continued). "When IL-6 binds to mIL6R, the membrane-bound form of IL-6R, it forms a complex comprising IL-6, IL-6R, and gp130; this complex activates Janus kinases (JAKs), thus triggering two main signaling pathways involved in autoimmune diseases." (PMID 39201060, 2024). "Interleukin-6 (IL-6) is a multifunctional cytokine that controls the immune response, and its role has been described in the development of autoimmune diseases." (PMID 38715108, 2024). "For example, IL-6-JAK-STAT3 is closely related to autoimmune diseases and tumors, and has become a hot target for drug research and development." (PMID 38698303, 2024). "The role of TNF-α and IL-6 in regulating immune system is well-described in inflammatory-mediated disorders, autoimmune diseases or infection." (PMID 38421574, 2024). "Using an integrative network approach, IL6 was identified as a promising target at the interface between MM and autoimmune diseases." (PMID 39408929, 2024). "Clinicians should be aware of the possibility of Castleman’s disease when faced with masses or enlarged lymph nodes in the parotid gland to avoid misdiagnosis, especially in patients with autoimmune diseases and elevated serum interleukin-6." (PMID 38566262, 2024). "In this regard, with aging there is an increase in pro-inflammatory cytokines, including IL-6, TNFα and NLRP3 inflammasome, which are associated with age-related diseases such as autoimmune diseases, cancer, and metabolic disorders." (PMID 38265117, 2024). "Interleukin-6 (IL-6) is a pleiotropic cytokine involved in the pathogenesis of several autoimmune diseases, and the relationship between IL-6 and gMG pathogenesis has been also explored in various studies." (PMID 38751878, 2024). "Interleukin 6 is mainly produced and significantly increases in infections and tissue injuries, supporting acute phase responses but also in autoimmune diseases." (PMID 39519568, 2024). "Increased levels of the inflammatory cytokine interleukin-6 (IL-6) are very often observed in autoimmune diseases and in inflammatory reactions in the organism." (PMID 39456713, 2024). "Insights into the mechanism of neutralization by the three antibodies can explain the distinct potency of these antibodies against IL6, a CK involved in metastasis, tissue invasion, and mediating inflammatory reactions in autoimmune diseases and cancer." (PMID 38789577, 2024). "Another cytokine of interest in our dataset, IL-6, already has a therapeutic inhibitor named Tocilizumab (anti–IL-6 receptor antibody) commonly used in autoimmune disease and FDA-approved for interstitial lung disease in systemic sclerosis." (PMID 39408800, 2024). "Multiple research projects indicate the essential roles of IL‐6, IL‐10, IL‐21, and IL‐17 in the pathogenesis of autoimmune diseases." (PMID 36271684, 2024). "Studies have found that tumor necrosis factor (TNF) and interleukin-6 (IL-6) are over-activated in autoimmune diseases and CKD." (PMID 38533318, 2024). "IL-1β enhances inflammation in the course of autoimmune diseases, and also has the ability to stimulate the production of IL-6." (PMID 39456713, 2024). "Biologics targeting specific cytokine pathways are widely used in the treatment of autoimmune diseases, including but not limited to Th2 cytokines (IL-4, IL-5, and IL-13), Th17 cytokines (IL-6, IL-17, and IL-23), and TNF-α." (PMID 39403935, 2024). "The involvement and overproduction of IL-6 has been reported in many autoimmune diseases, including MS." (PMID 38928437, 2024). "Important roles of interleukin (IL)-1β are found in autoinflammatory disorders, but roles of IL-6 are highlighted in autoimmune diseases and PMR21." (PMID 38177227, 2024). "The persistent dysregulated generation of IL-6 plays a vital function in RA development and other autoimmune disorders." (PMID 39741627, 2024).
autoimmune disease (continued). "Applying anti-IL-10 antibody or scFv secretion from a CAR Treg would likely have anti-inflammatory effects similar to an anti-IL-6 secreting Treg, but with the potential for further implementation in a wider variety of autoimmune diseases." (PMID 39445021, 2024). "Studies have indicated that the expression of tumor necrosis factor-alpha (TNF-α), interferon-gamma (IFN-γ), and several interleukins (such as IL-1, IL-6, IL-12, and IL-17) is elevated in autoimmune diseases, driving inflammation and tissue damage." (PMID 39104791, 2024). "Activation of classical (IL-6/IL-6R) or trans signaling (IL-6/sIL6R) occurs via gp130 and contributes to the sequestration of excess IL-6; blocking trans-signaling is effective in preclinical chronic and autoimmune diseases." (PMID 39553645, 2024). "Focusing on molecular uveitis, IL-6 is a cytokine showing elevated production in autoimmune diseases and infections." (PMID 38232093, 2024). "Conversely, other studies have shown that MSCs decrease levels of IL-1β, IL-17α, and IL-6 while increasing IL-10 levels in various autoimmune diseases." (PMID 39273184, 2024). "As observed in the majority of the reviewed articles, biomarkers like S100 proteins or the cross-activation of cytokines (IL-17, IL-18, IL-6) are evident across various autoimmune diseases." (PMID 38474052, 2024). "Although IL-6 has been extensively studied in autoimmune diseases, infections, and tumors, little research has been conducted on its role in ovarian function." (PMID 39639885, 2024). "Interleukin 6 (IL-6) plays a central role in the pathogenesis of autoimmune diseases, and its inhibition has been recently shown to be effective in treating the most severe cases of uveitis that are unresponsive even to anti-TNF agents." (PMID 37700264, 2023). "IL-6 is a well-known pleiotropic cytokine involved in pro-inflammatory immune responses, autoimmune diseases, senescence, and carcinogenesis." (PMID 37849764, 2023). "The sIL-6R-driven IL-6 trans-signaling has been mainly assigned as the pathological mode of IL-6 signaling that contributes to inflammatory, autoimmune diseases and cancer." (PMID 37838173, 2023). "IL-6 plays a role in regulating acute and chronic inflammatory responses in autoimmune disorders and endothelial cell dysfunction." (PMID 37515250, 2023). "In fact, the expression of IL-6 has been correlated with numerous other pathological conditions, such as infections, neoplasms and autoimmune diseases." (PMID 38003490, 2023). "Several biologics have been used for the treatment of IL6-related autoimmune diseases, such as Tocilizumab, Siltuximab, and Sarilumab." (PMID 38046810, 2023). "The literature is very broad in linking IL-6 directly with the pathophysiology of several autoimmune diseases." (PMID 36836567, 2023). "When induced by TGF‐β in conjunction with IL‐6, CD4+ T cells can differentiate into Th17 cells that secrete IL‐6 and IL‐17 and are involved in inflammatory responses and autoimmune diseases." (PMID 37506156, 2023). "University researchers are investigating IL-6 signaling mechanisms and its biological effects, while the company is focused on developing and characterizing IL-6 inhibitors for potential use in treating autoimmune diseases." (PMID 38137450, 2023). "Dysregulated IL-6-signaling contributes to the onset and persistence of several autoimmune diseases including IBD and promotes the development of various cancer types, e.g., CCA." (PMID 37256725, 2023). "IL-6 is an inflammation marker in certain autoimmune diseases, which plays a critical role in the recruitment of inflammatory cells and the modulation of the immune system." (PMID 37343193, 2023). "Dysregulation of IL-6 leads to an imbalance between Th17 and Treg cells, resulting in the development of autoimmune disorders." (PMID 37535585, 2023). "Increasing concentrations of TGF-β were found to inhibit IL-6-induced production of IL-22 in Th17 cells in a model of autoimmune disease." (PMID 38162671, 2023).